IL6 (interleukin 6)
Diseases named in the same sentence as IL6 in open-access papers (continued):
Sharing a sentence is not in itself a finding about the gene and the disease.
prediabetes (continued). "Physical activity promotion with dietary and lifestyle modification may reduce the level of leptin and interleukin-6, but we are uncertain if there is any effect on levels of adiponectin, C-reactive protein, and tumour necrosis factor-α in the individuals with prediabetes." (PMID 38068801, 2023). "This review suggests that physical activity promotion with dietary and lifestyle modification may reduce the level of leptin and interleukin-6 but are uncertain if there is any effect on levels of adiponectin, C-reactive protein and tumour necrosis factor-α in the individuals with prediabetes." (PMID 33211181, 2021). "We hypothesize that opioid peptides (endomorphin-2 (EM2), and β-endorphin (βEP)), and their receptors (μ-opioid receptors (MOR) and κ-opioid receptors (KOR)), in addition to the inflammatory cytokines (IL-6) and anti-inflammatory cytokine (IL-10), affect IR parameters in patients with prediabetes." (PMID 34099024, 2021). "This systematic review and meta-analysis demonstrate that probiotic and synbiotic supplementation effectively reduces inflammatory markers, including CRP, IL-6, and TNF-α, in adults with prediabetes and T2DM." (PMID 41022286, 2025). "miR-27 was up-regulated in obese prediabetes, targeting regulators of oxidative stress and apoptosis such as BCL2, BMI1, FOXO3, and suppressing SIRT1, thereby amplifying IL-6 production." (PMID 41400625, 2025). "IL-6 is an important pro-inflammatory cytokine, very often present in higher levels in individuals with T2DM and prediabetes." (PMID 41150802, 2025). "ROC curve analysis evaluated the predictive ability of four inflammatory markers-IL-18, TNF-α, IL-6, and NFATC4-for classifying prediabetes cases and controls." (PMID 40027364, 2024). "Receiver operating characteristic (ROC) curve analysis identified IL-18 and NFATC4 as the most promising biomarkers for predicting prediabetes, followed by TNF-α and IL-6." (PMID 40027364, 2024). "Results showed that normoglycaemic SAs had less non-esterified fatty acid (NEFA) suppression during the test, resembling prediabetes/T2D responses, and higher levels of plasma fetuin-A, CRP, and IL-6 but lower adiponectin, indicating AT inflammation." (PMID 38786765, 2024). "Meanwhile, this study showed that ACE2 was positively correlated with IL-6, FBG, and 2hPBG, especially with blood glucose, indicating that in prediabetes, ACE2 expression is mainly regulated by blood glucose." (PMID 36253996, 2022). "Pearson correlation analysis showed that ACE2 was positively correlated with IL-6, FBG, and 2hPBG levels in the prediabetes group." (PMID 36253996, 2022). "In this study, we firstly revealed the differences of adiponectin, nesfatin-1, IL-6, and TNF-α between prediabetes and T2DM or healthy individuals in Chinese population." (PMID 35311231, 2022). "The levels of IL-6 and TNF-α in the single crown group of prediabetes were 138 pg/mL and 98 pg/mL, respectively." (PMID 36557041, 2022). "Pearson correlation analysis showed that ACE2 was positively correlated with IL-6, FBG, and 2hPBG in prediabetes group (R = 0.271, 0.572, 0.843, P < .05 or P < .01)." (PMID 36253996, 2022). "Similar analysis in Indians showed significantly higher levels of inflammatory biomarkers like high-sensitive C-reactive protein (hsCRP), IL1β, IL13, IL17A, IL6, TNFα, and IAP in individuals with prediabetes compared to normoglycemic individuals." (PMID 33658065, 2021). "The IL-6, IL-10, β-endorphin, MOR, and endomorphin-2 were higher in the prediabetes subgroups than the control group." (PMID 34099024, 2021). "The objective was to investigate the association between periodontal status and whole salivary interleukin-6 (IL-6) concentrations in normal-weight and obese individuals with and without prediabetes." (PMID 42034767, 2026). "Similarly, IL-6 levels decreased significantly in individuals with T2DM and prediabetes with interventions lasting over 12 wk." (PMID 41022286, 2025).
prediabetes (continued). "This review suggests that the physical activity promotion program may reduce the level of leptin and IL-6, but whether there is any effect on the level of adiponectin, CRP, and TNF-α in individuals with prediabetes is uncertain." (PMID 38068801, 2023). "No significant variation of cytokines was observed between prediabetes and control group for IL-6, IL-10, IL-17A, IL-4, IL-8, IFN-γ, and TNF-α." (PMID 37457235, 2023). "Indeed, we have shown higher levels of IL-6 and fibrinogen in NT2D and T2D compared to prediabetes, as well as higher levels of CRP in prediabetes, NT2D and T2D compared to healthy controls." (PMID 37814622, 2023). "For this purpose, we assessed the relationship between serum Vit D levels and acute phase reactants such as CRP, fibrinogen and ferritin and pro-inflammatory markers such as IL-1β, IL-6, IL-8, TNF-α, NF-κB and MAPK in newly diagnosed prediabetes and type 2 DM patients." (PMID 38136648, 2023). "The IL-6, IL-10, βEP, MOR, and EM2 were higher in the prediabetes." (PMID 34099024, 2021). "This review suggests that physical activity promotion programme may reduce the level of leptin and IL-6, but it is uncertain whether there is any effect on the level of adiponectin, CRP and TNF-α in individuals with prediabetes." (PMID 33211181, 2021). "In prediabetes groups, IL-6 was significantly elevated compared to the control group, whereas there was no such difference between the prediabetes subgroups." (PMID 34099024, 2021). "Although we observed no overall change in skeletal muscle or serum IL-6 with exercise training, reductions in muscle IL-6 were tied to increased muscle mass more closely in subjects with prediabetes compared with RA." (PMID 30587230, 2018). "In this case control study, we aimed to probe into the differences and connections of adiponectin, nesfatin-1, IL-6, and TNF-α levels in prediabetics, T2DM, and the normal participants in order to better understand the roles of these cytokines in the development of prediabetes and T2DM." (PMID 35311231, 2022). "To examine these hypotheses, we measured serum levels of some opioids proteins and receptors in addition to IL-6 and IL-10 levels in prediabetes patients who have/have not an IR state and compared with the healthy controls." (PMID 34099024, 2021). "In LOsG-induced prediabetes, although pancreatic ROS stress remained high on LOsG treatment day 38, there were no alterations in mRNA levels of ER stress (XBP1 and BIP), inflammation (IL6 and IL1β), and hypoxia-responsive (HIF1α and GAPDH) genes between LOsG- and sham-treated groups." (PMID 30975975, 2019). "IL1-β, IL-6, IL-8, TNF-α, NF-κB, and MAPK were also significantly increased in the T2D and prediabetes groups compared to non-diabetic groups, indicating their role as pro-inflammatory factors." (PMID 39568808, 2024). "We expected to see worsened clinical and radiographic picture and elevated levels of IL-6 and TNF-α in the PICF of prediabetes as compared to the non-diabetic individuals." (PMID 36557041, 2022). "This study revealed that the IL1-β, IL-6, IL-8, TNF-α, NF-κB and MAPK levels as pro-inflammatory markers and CRP, fibrinogen and ferritin as serum acute phase reactants were significantly increased in the prediabetes and T2DM groups compared to nondiabetes group." (PMID 38136648, 2023). "Materials and Methods: The clinical and radiographic parameters and the levels of IL-6 and TNF-α in the peri-implant crevicular fluid (PICF) of narrow diameter single (NDISCs) and splinted (NDISPs) crown implants were assessed both in non-diabetics and participants with prediabetes." (PMID 36557041, 2022).
keloid (64 papers, 2009 to 2026). An irregularly shaped, elevated mark on the skin caused by deposits of excessive amounts of collagen during wound healing. "Their finding suggests that the IL-6 −572 G/C polymorphism is significantly associated with susceptibility to keloid formation and severity of keloid scarring, thus providing insight into strategies for the prediction and prevention of keloid formation." (PMID 39799030, 2025). "IL-6 produced by fibroblasts has been linked to the pathogenesis of fibrosis in abnormal wound-healing lesions such as keloid." (PMID 39799030, 2025). "The higher serum levels of IL-6 were associated with the GG genotype, which was significantly higher in keloid patients and increased the risk for keloid development." (PMID 39799030, 2025). "A Japanese study showed the IL-6 polymorphism and susceptibility to keloid formation in a Japanese population." (PMID 39799030, 2025). "The mechanism of keloid ECM alignment is initiated by autocrine IL-6 production causing patterning and alignment of the fibroblasts themselves." (PMID 37660739, 2023). "IL-6 and TNFα, which were upregulated by FnIII-1c in both skin fibroblast lines, have been implicated in the development of keloid and hypertrophic scars." (PMID 37228128, 2023). "In brief, the IL-6 signaling pathway has been implicated in both hypertrophic scars and keloid pathogenesis." (PMID 36147459, 2022). "For instance, a significant association between IL-6 572 gene polymorphism and its serum level was reported in Egyptian patients with keloid." (PMID 35905107, 2022). "Ogawa (2017) suggested that keloids and hypertrophic scars are derived from an abnormal inflammatory reaction in the skin since proinflammatory factors, including IL-1α, IL-1β, IL-6, and TNF-α, are associated with keloid formation." (PMID 33282860, 2020). "Notably, IL6 emerged as a central hub within the keloid-associated PPI network, implicating its pivotal role in keloid pathogenesis." (PMID 41544047, 2026). "Similarly, another Chinese study also found that the IL-6 -572C > G polymorphism was closely associated with the incidence of keloid." (PMID 39799030, 2025). "This raises the question of whether the rs1800797, rs1800796, and rs1800795 polymorphisms in the IL6 gene promoter or the functional rs2228145 polymorphism of the IL6R gene predispose patients of European descent to keloid formation." (PMID 38791322, 2024). "In addition, IL-6 polymorphisms have been associated with susceptibility to keloid formation across populations." (PMID 37033989, 2023). "IL-6 produced by fibroblasts is involved in the pathogenesis of fibrosis associated with rheumatoid arthritis, progressive scleroderma, interstitial pulmonary fibrosis and lesions with abnormal wound healing such as keloids." (PMID 36406661, 2022). "The production of IFN-γ in the serum of normal patients was higher than keloid persons, which may cause keloid formation by increasing IL-6 secretion." (PMID 33959031, 2021). "IL-6 levels are observed to be increased in fibroblasts from a number of skin pathologies, and a genome-wide association study uncovered a single-nucleotide polymorphism in keloid patients that may lead to hyperactivated signaling in fibroblasts (originally termed the IL-6 amplifier)." (PMID 37660739, 2023). "Elevated IL6 levels have been consistently reported in keloid tissues, with studies confirming increased IL6 secretion by cultured keloid fibroblasts into conditioned media." (PMID 41544047, 2026). "The increase of proinflammatory cytokines, such as TNF-α, IL-1 and IL-6, in keloid tissue, indicated that localized inflammatory response is present in patients with keloids." (PMID 41556665, 2026). "The dual role of IL6 underscores its centrality in keloid pathogenesis, connecting bioinformatics predictions with TCM pharmacology." (PMID 41544047, 2026).
keloid (continued). "AMPH and TNFRSF9 are promising diagnostic biomarkers for keloid, while quercetin from Aloe vera targets HAS2 and IL6, offering therapeutic potential." (PMID 41544047, 2026). "These cells are responsible for the production of key cytokines, including interleukin 6, −17 and transforming growth factor‐beta (TGF β1 and ‐β2), particularly in individuals predisposed to keloid development." (PMID 39895409, 2025). "IL-17, a pro-inflammatory cytokine, is secreted by a distinct subtype of activated CD4+T-cells known as Th17.26, 27 Tumor-like stem cells derived from human keloids are governed by the inflammatory niche driven by the IL-17/IL-6 axis." (PMID 39799030, 2025). "In vivo studies using mouse and rabbit scar models, as well as a nude mouse keloid xenograft model, revealed that these ASOs effectively reduced scar formation and keloid growth while also suppressing IL-6 expression." (PMID 40918506, 2025). "The expression of TNF‐α, IL‐1β, and IL‐6—key inflammatory cytokines involved in keloid formation—was measured, and the biocompatibility of CNDS@Simvastatin was evaluated to ascertain its impact on important organs." (PMID 39313951, 2025). "The mRNA and protein expressions of gp130 and several downstream targets in IL-6 signaling were upregulated in keloid fibroblasts." (PMID 39799030, 2025). "Global gene expression analysis of keloid fibroblasts revealed the involvement of the interleukin-6 pathway." (PMID 39799030, 2025). "Previous studies have demonstrated that IL-6 stimulates the phosphorylation of pY705 STAT3 in keloid fibroblasts to a significantly higher degree than in normal fibroblasts." (PMID 38284901, 2024). "In our study, p-STAT3 expression significantly increased in keloid fibroblasts following exogenous IL-6 stimulation, but this elevated p-STAT3 was significantly suppressed by DMC-HA intervention." (PMID 38284901, 2024). "Subsequent addition of DMC-HA resulted in a reduction in p-STAT3 levels induced by exogenous IL-6 in keloid fibroblasts, as evidenced by Western blot analysis (P<0.05)." (PMID 38284901, 2024). "Curcumin has been shown to inhibit the production of inflammation-related cytokines such as tumor necrosis factor-α (TNF-α), interleukin-1β (IL-1β), and interleukin-6 (IL-6), all of which play pivotal roles in keloid formation." (PMID 38284901, 2024). "Excessive activation of interleukin-6-dependent signal transduction seems to play an important role in the pathogenesis of keloid scarring." (PMID 38791322, 2024). "first documented increased expression of IL-6 and its receptor in keloid fibroblasts, together with a large number of collagen fibers in the dermis." (PMID 38476235, 2024). "IL-6, IL-1β, IL-1α, and IL-8 are highly expressed in keloid fibroblasts, and induce the expression of TGFβ1 or render scars more sensitive to external stimuli, thus contributing to the continuous scar expansion and keloid formation." (PMID 38338767, 2024). "The inhibition of STAT3 expression to block IL-6’s signaling pathway or inhibit IL-6 in keloid fibroblast cultures has resulted in keloid tissue fibroblasts losing collagen production, impairing their proliferation." (PMID 39091289, 2024). "Only in the study of IL6 rs1800796 among Egyptians was the group size (90 adults, including 60 patients with keloid scars) much smaller than in our report." (PMID 38791322, 2024). "IL-6, IL-6R, and gp130, are greatly elevated in keloid fibroblasts compared to those in normal skin." (PMID 39091289, 2024). "Downstream of IL-6, supracellular organization of keloid fibroblasts is controlled by activation of cell-cell adhesion." (PMID 37660739, 2023). "In contrast to TGF-β, the cytokine IL-6 has consistently been reported to be elevated in keloid scars." (PMID 37660739, 2023). "First, the expressions of genes highly upregulated in keloid tissue, IL-6, CTGF and COL1A2, were enhanced in keloid marginal fibroblast–transplanted tissue, and this expression was suppressed by vismodegib." (PMID 38062202, 2023).
keloid (continued). "Immunotherapies that target IL-6 signaling, such as tocilizumab, sarilumab, and siltuximab, should be further investigated in keloids." (PMID 37895153, 2023). "IL-6 can also promote epithelial-mesenchymal transition (EMT) via the JAK/STAT pathway in keloid pathogenesis." (PMID 37587491, 2023). "A mechanistic study showed that IL-6 maintains the chronic profibrotic state via a Th1-mediated immune response in keloids, and the IL-17/IL-6 axis is also dysregulated." (PMID 37587491, 2023). "Of note, several experimental therapies for keloids and other forms of cutaneous fibrosis directly or indirectly antagonize IL-6." (PMID 37033989, 2023). "Downstream of IL-6, keloid cells generate cell-cell adhesions that create a supracellular actin network leading to monolayering and alignment of the population." (PMID 37660739, 2023). "By sustaining the expression of CCL2, CSF1, and IL-6, fibroblasts give signals for the chemotaxis, residency, and activation of macrophages in keloids." (PMID 37895153, 2023). "TNF-α-stimulated gene-6 (TSG-6), a protein suppressed in keloid fibroblasts, has been shown to attenuate IL-1β, IL-6, and TNF-α when intradermally injected into hypertrophic scars." (PMID 37033989, 2023). "Cytokines enriched in the keloid microenvironment, especially IL-6 and OSM, are strong activators of the JAK/STAT system." (PMID 37033989, 2023). "Similar to patients with systemic sclerosis, patients with keloids show elevated IL-6 in the serum and skin." (PMID 37033989, 2023). "Collectively, this demonstrates that keloid fibroblasts, through IL-6-induced intercellular cooperativity, actively remodel the ECM to generate anisotropy in the network." (PMID 37660739, 2023). "Inhibiting IL-6 or IL-6 receptor α (IL-6Rα) in keloid fibroblasts revealed a dose-dependent decrease in collagen type I α 2 and fibronectin 1 mRNAs." (PMID 37895153, 2023). "The reticular dermis has been proposed as the main locale of chronic inflammation underscoring the formation of keloid scars with upregulation of various proinflammatory cytokines, including IL-1α, IL-1β, IL-6, and tumor necrosis factor (TNF)-α." (PMID 37033989, 2023). "IL-6 is a key cytokine with a proinflammatory function and its mediated inflammatory response is a key factor in the pathogenesis of keloids." (PMID 36406661, 2022). "IL-6 has been shown to promote proliferation and collagen synthesis in keloid-derived fibroblasts, thus participating in keloid pathogenesis." (PMID 36248839, 2022). "In a clinical study, blood IL-6 expression was significantly increased in patients with a family history of keloids." (PMID 36406661, 2022). "IL-6 secretion was higher in HS and keloid, and the mRNA and protein levels of IL-6R α and IL-6R β (gp130) and its downstream targets LAK1, STAT3, RAF1 and ELK1 were up regulated." (PMID 33959031, 2021). "Currently, several treatments for HS and keloid are known to regulating the expression and/or secretion of IL-6." (PMID 33959031, 2021). "While shikonin inhibited scratch closure and IL-6 production in keloid line cells, the mechanism of action is unclear given shikonin failed to impact vimentin expression and had less pronounced impacts on metabolism." (PMID 34143844, 2021). "Another group reported an increase in chemokine-like factor 1 and other pro-inflammatory cytokines, such as IL-6, IL-8, and IL-18, in keloid tissue compared to normal skin and normal scars." (PMID 33123623, 2020). "One report identified up-regulation of the proinflammatory cytokines, IL-1α, IL-1β, IL-6, and TNFα, in keloid fibroblasts." (PMID 33329590, 2020). "The development of keloids is accompanied by changes in inflammatory factors, such as interleukin (IL)-6, IL-1, IL-8 and tumour necrosis factor-α (TNF-α)." (PMID 28498357, 2017). "Compared to normal wounds or skin, keloids are highly enriched in growth factors, extracellular matrix, and inflammatory cytokines such as IL-6 and TGFβ." (PMID 21436892, 2011).